F8 (coagulation factor VIII)
Diseases named in the same sentence as F8 in open-access papers (continued):
Sharing a sentence is not in itself a finding about the gene and the disease.
COVID-19 (45 papers, 2020 to 2025). A disease caused by infection with severe acute respiratory syndrome coronavirus 2. "In our proteomic analysis, C4b (C4b-binding protein beta chain) and coagulation factor VIII were upregulated in COVID-19 patients." (PMID 35937696, 2022). "vWF, an adhesive glycoprotein synthesized by endothelial cells and megakaryocytes, and coagulation factor VIII seems to be the main players in AIS COVID-19 clot formation in our study." (PMID 36704480, 2022). "COVID-19 patients show a broad spectrum of endothelial alterations, such as an increase in the activity of coagulation factor VIII and a high increase in von Willebrand factor and angiotensin II level in the plasma, associated with viral load and lung damage." (PMID 34001199, 2021). "We could only highlight a slight elevation in coagulation factor VIII (199%), in line with the inflammatory context of COVID-19." (PMID 35743512, 2022). "ABO(H) glycans on the viral S protein or lung epithelial cells may impact viral infection, while ABO(H) antigens on von Willebrand factor (vWF) and coagulation factor VIII (FVIII) are known to impact thromboembolic risk, which may impact COVID-19 disease severity." (PMID 36696414, 2023).
thrombophilia (44 papers, 2012 to 2026). A condition characterized by an abnormally high level of thrombi. "The inherited thrombophilias include factor V Leiden, prothrombin G20210A, antithrombin deficiency, protein C deficiency, protein S deficiency, and elevated coagulation factor VIII (FVIII), while acquired thrombophilias include the presence of antiphospholipid antibodies." (PMID 23762560, 2013). "Normal thrombophilia study findings after the acute process, except for a minimal persistent elevation of coagulation factor VIII activity, are in accordance with an independent procoagulant state and SARS-CoV-2-derived coagulopathy." (PMID 35743512, 2022). "A hypercoagulable state was observed in both the patients with a high level of VWF and VWF:RCo, D-dimer, and coagulation Factor VIII." (PMID 34341358, 2021). "In our work, considering the scant number of patients with a thrombophilia study, no relevant alterations were detected, with the exception of a minimal persistent elevation in coagulation factor VIII activity." (PMID 35743512, 2022).
coagulopathy (37 papers, 2012 to 2026). "AHA is a rare coagulopathy caused by the presence of autoantibodies directed against the coagulation factor VIII (FVIII), resulting in an increased risk of bleeding, which can be severe." (PMID 37830631, 2023). "Hemophilia A (HA) is an X-linked recessive blood coagulation disorder caused by mutations in the coagulation F8 gene, which encodes for the blood coagulation factor, FVIII." (PMID 34439937, 2021). "HA is a coagulation disorder characterized by partial or total deficiency of factor FVIII, caused by mutations in the gene encoding coagulation factor VIII." (PMID 36428936, 2022). "Coagulopathy in a cirrhotic patient is related to a reduction of coagulation factors, and the presence of anti-coagulants, thrombocytopenia, deficit of factor VII, and increased plasma levels of coagulation factor VIII and Von Willebrand factor." (PMID 33620540, 2021). "The defect regards the F8 gene product – coagulation factor VIII, the lack of which leads to coagulation disorders." (PMID 32894158, 2020).
Von Willebrand disease (33 papers, 2009 to 2026). von Willebrand disease (VWD) is a hereditary bleeding disorder caused by a genetic anomaly leading to quantitative, structural or functional abnormalities of the Willebrand factor (von Willebrand factor; VWF). "In addition, synthetic AVP (desmopressin) is used as procoagulant treatment, for example, in von Willebrand’s disease (vWD), as it increases platelet release of coagulation factor VIII and von Willebrand factor after administration." (PMID 34156969, 2021).
autoimmune disease (29 papers, 2013 to 2025). A disorder resulting from loss of function or tissue destruction of an organ or multiple organs, arising from humoral or cellular immune responses of the individual to their own tissue constituents. "Acquired hemophilia A (AHA) is a rare autoimmune disease caused by an antibody that inhibits coagulation factor VIII activity." (PMID 39093750, 2024). "Acquired hemophilia A (AHA) is a rare autoimmune disease caused by autoantibodies against coagulation factor VIII and characterized by spontaneous hemorrhage in patients with no previous family or personal history of bleeding." (PMID 36466121, 2022). "Acquired haemophilia A (AHA) is an autoimmune disease caused by the spontaneous production of neutralising immunoglobulin G autoantibodies directed against functional epitopes of endogenous coagulation factor VIII (FVIII)." (PMID 40052437, 2025). "Acquired Hemophilia A (AHA) is a rare autoimmune disorder characterized by the emergence of inhibitors that specifically target coagulation Factor VIII, frequently resulting in severe bleeding episodes." (PMID 38846411, 2024). "Acquired hemophilia A (AHA) is an autoimmune disorder characterized by the spontaneous emergence of autoantibodies against coagulation Factor VIII, leading to a rare, yet serious bleeding disorder." (PMID 38846411, 2024). "Acquired hemophilia A (AHA) is an ultra-rare autoimmune disorder characterized by the development of autoantibodies against coagulation factor VIII (FVIII)." (PMID 36819387, 2023). "Acquired hemophilia A (AHA) is a rare autoimmune disease where autoantibodies decrease the activity and plasma half-life of coagulation factor VIII (FVIII), resulting in bleeding." (PMID 34347197, 2021).
venous thromboembolism (18 papers, 2014 to 2025). Occlusion of the lumen of a vein by a thrombus that has migrated from a distal site via the blood stream. "Von Willebrand factor (VWF) and coagulation factor VIII (FVIII) plasma levels are associated with increased risk for venous thromboembolism (VTE)." (PMID 40488174, 2025). "Previous studies had reported that low serum iron levels were associated with elevated plasma levels of coagulation factor VIII, which might contribute to venous thromboembolism risk." (PMID 33195696, 2020).
hemarthrosis (15 papers, 2014 to 2026). Bleeding into the joints. "Coagulation factor VIII deficient (FVIII−/−) mice develop an osteoporotic phenotype in the absence of induced hemarthrosis that is exacerbated two weeks after an induced joint injury." (PMID 31594977, 2019).
diabetes (14 papers, 2014 to 2025). "Patients with diabetes usually experience increased coagulation factor VIII and increased platelet function, which will further accelerate the formation of atherosclerotic thrombosis and cause arterial lumen occlusion." (PMID 36698925, 2022).
coronary artery disease (11 papers, 2011 to 2025). "Conversely, the elevated plasma concentrations of coagulation factor VIII and von Willebrand factor in non-O blood-group individuals has been implicated in the increased risk for thromboembolic disease and ischemic heart disease." (PMID 21799738, 2011).
endothelial dysfunction (11 papers, 2016 to 2024). In vascular diseases, endothelial dysfunction is a systemic pathological state of the endothelium (the inner lining of blood vessels) and can be broadly defined as an imbalance between vasodilating and vasoconstricting substances produced by (or acting on) the endothelium. "That other circulating markers of endothelial dysfunction such as coagulation factor VIII, E-selectin, intercellular adhesion molecule-1, and tPA have also been found to predict T2D10, 33, 34, 35, 36, 37, also supports a role of PAI-1 in the pathogenesis of T2D." (PMID 26813008, 2016).
breast carcinoma (8 papers, 2013 to 2025). "Some studies have shown that the expression of F8 is high in multiple myeloma, breast cancer, and colorectal cancer." (PMID 33718231, 2021).
Obesity (8 papers, 2021 to 2025). Accumulation of substantial excess body fat. "It is noteworthy that other factors, such as obesity, coagulation factor VIII, and maternal anxiety, which demonstrated significant differences in our univariate analysis, were not retained as independent predictors in the final multivariable model." (PMID 41585786, 2025). "After adjustment for age, obesity and smoking, VTE risk was associated with coagulation factor VIII, factor IX, von Willebrand factor (VWF), activated partial thromboplastin time (APTT), and fibrin D‐dimer." (PMID 35655415, 2022).
Thrombocytopenia (8 papers, 2013 to 2025). A reduction in the number of circulating thrombocytes. "The recently developed novel strategy of IO delivery of F8-LVs can efficiently transduce bone marrow cells and express FVIII in HSCs without the requirement of using potentially toxic, myelosuppressive pre-conditioning methods and the risk of inducing thrombocytopenia." (PMID 27766066, 2016).
lymphoma (6 papers, 2005 to 2025). A malignant (clonal) proliferation of B- lymphocytes or T- lymphocytes which involves the lymph nodes, bone marrow and/or extranodal sites. "Perioperative treatment with octanate® (human coagulation factor VIII) enabled the successful performance of all surgical interventions required in the context of lymphoma treatment." (PMID 32257466, 2020). "Activation of coagulation in patients with cancer including malignant lymphoma has been observed in earlier reports, namely increased prothrombin activation, elevation of coagulation factor VIII (F VIII) and impairment of platelet function." (PMID 15798767, 2005).
Autoimmune (5 papers, 2013 to 2025). "Acquired haemophilia A (AHA) is a rare autoimmune disorder caused by autoantibodies against coagulation factor VIII (FVIII), resulting in significant bleeding risks." (PMID 40323009, 2025). "Acquired haemophilia A (AHA) is a rare and life‐threatening autoimmune disorder characterized by the development of autoantibodies against coagulation factor VIII (FVIII)." (PMID 40323009, 2025).
acquired von willebrand syndrome (4 papers, 2015 to 2023). "Acquired von Willebrand syndrome and hemolysis were observed approximately one year after implant and were treated by a slight reduction in anticoagulation therapy and intravenous Haemate P (coagulation factor VIII)." (PMID 26253585, 2015).
intracranial hemorrhage (4 papers, 2021 to 2024). Bleeding within the SKULL, including hemorrhages in the brain and the three membranes of MENINGES. "Affected males suffer from spontaneous soft-tissue, muscle and joint bleeding symptoms, the severe patients (coagulation factor VIII (FVIII) activity <1% of the normal value) even experience life-threatening intracranial hemorrhage." (PMID 36968612, 2023).
pulmonary arterial hypertension (4 papers, 2010 to 2023). Pulmonary arterial hypertension (PAH) is a group of diseases characterized by mean pulmonary artery pressure >20 mmHg and elevated pulmonary arterial resistance leading to right heart failure. "Elevated levels of coagulation factor VIII have been found in CTEPH but have also been associated with pulmonary arterial hypertension (PAH)." (PMID 38255153, 2023).
rheumatoid arthritis (4 papers, 2009 to 2023). A chronic, systemic autoimmune disorder characterized by inflammation in the synovial membranes and articular surfaces. "In this article, we have compared four human monoclonal antibodies specific to alternatively-spliced components of the extracellular matrix and have identified F8 as a suitable candidate for pharmacodelivery applications in rheumatoid arthritis." (PMID 19781067, 2009).
coagulation factor deficiency (3 papers, 2014 to 2025). "As a rare hemorrhagic disorder but the most frequently acquired coagulation factor deficiency, AHA is caused by the development of antibodies, referred to as “inhibitors,” against coagulation factor VIII (FVIII), which neutralize FVIII activity." (PMID 24741588, 2014).
Arthritis (2 papers, 2009 to 2022). Inflammation of a joint. "The F8 antibody sometimes exhibited a diffuse stromal staining or a vascular staining pattern, but consistently reacted strongly with both human and murine specimens of arthritis and was thus selected for pharmacodelivery applications." (PMID 19781067, 2009).
Turner syndrome (2 papers, 2017 to 2023). Turner syndrome is a chromosomal disorder associated with the complete or partial absence of an X chromosome. "Eight TFs and four ERFs are among the differentially expressed genes, as well as eight genes associated with Turner syndrome (PROCR, NR3C1, INSR, APOB, BMP15, F8, IL6, and WAS) and two genes that are haploinsufficient in humans (RAD50 and SLC33A1)." (PMID 28818098, 2017).
angioedema (1 paper, 2023). Swelling involving the deep dermis, subcutaneous, or submucosal tissues, representing localized edema. "In addition to the overlapped pathways, the knowledge-statistical network uncovered a new set of pathways related to dysregulation of hemostasis like platelet aggregation (Plug Formation), defective factor XII causes hereditary angioedema and defective F8 cleavage by thrombin." (PMID 36720931, 2023).
chronic thromboembolic pulmonary hypertension (1 paper, 2023). Chronic thromboembolic pulmonary hypertension (CTEPH) is characterized by the persistence of thromboemboli in the form of organized tissue obstructing the pulmonary arteries. "Chronic thromboembolic pulmonary hypertension (CTEPH) is associated with thrombotic states including elevated coagulation factor VIII (FVIII)." (PMID 36890726, 2023).
Japanese encephalitis (1 paper, 2020). A disease due to a virus transmitted by an arthropod). "Also, BHK was used in the production of recombinant proteins, such as blood coagulation factor VIII for the extraction of DNA from Pseudorabies virus and production of capture antigen enzyme-linked immunosorbent assay (ELISA) when diagnosing Japanese Encephalitis (JE)." (PMID 32742521, 2020).
ovarian carcinoma (1 paper, 2013). A malignant neoplasm originating from the surface ovarian epithelium. "The protein expression levels of VEGF and its receptors, Flt-1 and KDR/Flk-1, were detected in 48 cases of ovarian cancer using the streptavidin-biotin complex (SABC) immunohistochemical method, and tumor MVD was evaluated using F8 factor (FVIII-RA)." (PMID 23946799, 2013).
schizophrenia (1 paper, 2014). A major psychotic disorder characterized by abnormalities in the perception or expression of reality. "In schizophrenia-coagulation network, the SCZCGs including F8, FN1 and FGL1 are differential expressed candidate genes which are associated with coagulation function." (PMID 25522158, 2014).
cancer (40 papers, 2005 to 2025). A tumor composed of atypical neoplastic, often pleomorphic cells that invade other tissues. "On the other hand, the acute phase reaction that accompanies cancer, may also cause the elevation of other pro-coagulant proteins, in particular the coagulation factor VIII (FVIII)." (PMID 30650562, 2019). "In addition, siRNA-mediated silencing of all transcripts of eight genes that showed a consistent differential splicing signature across multiple cancer types (ABCC5, ANKHD1, DYNLL1, F8, RPL31, TMEM14C, UQCC, and CRNDE) failed to reveal differences in cell viability." (PMID 25424858, 2015).
tumor (40 papers, 2006 to 2025). "We demonstrate that F8-SIP binds specifically to tumor vessels in a time and blood flow dependent manner." (PMID 29963235, 2018). "Histologically the tumor cells are positive for vascular markers such CD 31, CD 34, and coagulation factor VIII." (PMID 23533842, 2013). "Similarly, the F8 antibody, which is specific to EDA-FN, has been studied as a ligand for tumor-selective immunotherapies." (PMID 36899821, 2023). "Tumor cells were negative for muscle-specific actin, epithelial membrane antigen, smooth muscle actin, cytokeratin pan, S100, desmin, glial fibrillary acidic protein, myogenin, MyoD1 and F8." (PMID 24758544, 2014).
infection (22 papers, 2009 to 2025). The state of being infected such as from the introduction of a foreign agent such as serum, vaccine, antigenic substance or organism. "Additionally, known as antihemophilic factor (AHF) or FIXa cofactor, F8 transcript was found to be upregulated during the course of infection with Mayinga strain, but this increase was transient with the Makona and RESTV strains." (PMID 33917562, 2021). "In dogs, levels of several Ig-like domain-containing proteins were increased over the course of infection, and coagulation factor VIII at d230, while these were not increased in foxes at any time points." (PMID 34832667, 2021).
cardiovascular disease (9 papers, 2011 to 2025). "The proposed mechanism believed to underlie how ABO blood group may influence cardiovascular disease risk involves the possible regulatory effect of ABO antigens on plasma levels of von Willebrand factor (VWF) and coagulation factor VIII (FVIII)." (PMID 29780641, 2018).
F8 also shares sentences with these, for which no sentence is quoted: hemophilia B (77 papers); genetic disorder (19); arthropathy (16); Stroke (13); Hypertension (9); lupus (9); Thromboembolism (9); Cirrhosis (8); hemorrhage (8); liver disease (8); myocardial infarction (8); Sepsis (8); anemia (7); atrial fibrillation (6); blood disorder (6); antiphospholipid syndrome (5); factor deficiency (5); Hepatitis (5); hyperthyroidism (5); ischemic stroke (5); osteoporosis (5); pulmonary embolism (5); thromboses (5); AIDS (4); Arterial thrombosis (4); Cognitive impairment (4); cystic fibrosis (4); hypothyroidism (4); lung carcinoma (4); Menorrhagia (4).
A further 184 diseases each share a sentence with F8 in 4 papers or fewer.